AR (androgen receptor)
Diseases named in the same sentence as AR in open-access papers (continued):
Sharing a sentence is not in itself a finding about the gene and the disease.
breast carcinoma (continued). "We also explored a non-invasive radiomics-based method to detect AR expression, which might help develop a more comprehensive treatment strategy for patients with breast cancer." (PMID 34490107, 2021). "For instance, AR inhibitors, which can be cardioprotective, would be predicted to be more effective in Her2-amplified breast cancer responsive to trastuzumab/pertuzumab/lapatinib, while inhibitors of Rlip should be more effective in AU565 that should generate more GS-HNE." (PMID 34944997, 2021). "Moreover, inhibition of USP14 increased AR degradation and suppressed the AR-mediated signalling pathway to enhance the sensitivity of AR-positive breast cancer to AR antagonist (enzalutamide)." (PMID 34420039, 2021). "Moreover, FOXA1 expression is more highly correlated with AR than ER expression in breast cancer, suggesting the dual functions of FOXA1 in AR-positive versus ER-positive disease." (PMID 34680352, 2021). "AR expression and action differ among the various breast cancer subtypes." (PMID 35008851, 2021). "GT0918 can effectively inhibit AR-positive breast cancer tumor growth." (PMID 34392453, 2021). "Studies have provided evidence that AR also plays an important role in breast cancer." (PMID 34488823, 2021). "However, administering higher and lower than normal doses of MPA has opposing biological effects on breast cancer proliferation due to their effects on the AR signaling pathway." (PMID 34779589, 2021). "Therefore, it is very critical to develop new strategies for clinical studies of AR-targeted therapies for breast cancer and to identify the subgroup that is most likely to benefit from AR-targeting therapies." (PMID 34392453, 2021). "Androgen Receptor (AR) plays a significant role in 90% of all breast cancers." (PMID 35053185, 2021). "Importantly, AR-targeted therapies, including the AR antagonist, enzalutamide, have been demonstrated to be effective against breast cancer." (PMID 34575114, 2021). "The combination of different expressions of ER, PR, AR, GCDP-15 and Ki67 could be a risk factor in the development of breast cancer." (PMID 34066838, 2021). "Indeed, CBP/p300 are critical co-activators for the androgen receptor (AR) and estrogen receptor (ER) signaling in prostate and breast cancer, respectively." (PMID 34201346, 2021). "DIM is a natural small-molecule anti-cancer drug that has been shown to inhibit cell proliferation and induce cell apoptosis in prostate and breast cancer cells through the regulation of the Akt/FOXO3a/GSK-3/β-catenin/AR signaling axis and reduction of NF-κB activity." (PMID 33842314, 2021). "Furthermore, our study reveals that p68 mediates the effects of PDGFR-β in regulation of androgen receptor (AR) in breast cancer cells." (PMID 34659545, 2021). "Since the role of AR in involvement of breast cancer is unclear, it has been contentious whether AR agonists or antagonists should be used in the treatment." (PMID 33915941, 2021). "We then built 120 diagnostic models using distinct classification algorithms and feature sets divided by MRI sequences and selection strategies to predict molecular subtype and AR expression of breast cancer in the testing dataset of leave-one-out cross-validation (LOOCV)." (PMID 34490107, 2021). "Some MRI-based radiomics predictors could non-invasively predict molecular subtype and AR expression in breast cancer." (PMID 34490107, 2021). "Thus, IU1 in combination with enzalutamide offers an efficient strategy to suppress AR+ breast cancer growth." (PMID 34575114, 2021). "Interestingly, AR agonist treatment in breast cancer models reprograms binding of both FOXA1 and ESR, suggesting some degree of antagonistic function between the androgen and estrogen receptors." (PMID 34227937, 2021).
breast carcinoma (continued). "We found that SDH repression inhibits proteasomal degradation of AR by upregulating p‐Hsp27, findings consistent with studies in breast cancer, where SDH repression can also upregulate estrogen receptor (ER) β expression and promote mitochondrial biogenesis via PGC1α." (PMID 33709547, 2021). "In most of the breast cancer studies, the expression levels of the identified miRNAs were not investigated in association with AR expression." (PMID 34768979, 2021). "Furthermore, MPA displays a high affinity for androgen receptor (AR), and it can affect the proliferation of breast cancer cells through the AR signaling pathway." (PMID 34779589, 2021). "It was also found to be an androgen-responsive gene in AR-positive breast cancer." (PMID 33915941, 2021). "These secreted factors may be particularly useful in breast cancer patients with metastatic disease resistant to traditional therapies, where AR targeting drugs are being evaluated in multiple ongoing clinical trials." (PMID 34736512, 2021). "However, no published study reported the accuracy of MRI combining with radiomics in predicting AR expression and explored the importance of different MRI sequences in predicting molecular subtype of breast cancer." (PMID 34490107, 2021). "As androgen receptor pathway activation has been found to promote a subset of breast cancer, the role of KLK3 involved in tumor progression may need further investigation." (PMID 34650974, 2021). "In order to understand the translational relevance of MR inhibition by BC-N102, we evaluated the differential expression profile of PR, AR, and MR genes and found that PR and AR were over-expressed while MR gene is under-expressed in breast cancer patients compared to normal tissue." (PMID 34421361, 2021). "Furthermore, AR expression is variable in different subtypes of breast cancer, and high AR expression was reported in about 75% of HR+ cases, 50–60% of HER2+ cases, and 20–40% of TNBC cases, respectively." (PMID 34490107, 2021). "Indeed, the available data on the role of androgens/AR in preventing or promoting breast cancer are still controversial." (PMID 35008851, 2021). "Moreover, the AR acts as a tumour suppressor in the diverse setting of ERα+ breast cancer, including endocrine-resistant cancers." (PMID 35008851, 2021). "This association, and the recent description of FOXA1 as a determinant of chemotherapy resistance in breast cancer cells, strengthen the rationale of trials to evaluate the combination of androgen receptor-targeting agents with new-generation anti-HER2 targeted therapies." (PMID 34885167, 2021). "AR expression in breast cancer can vary from 53% to 93% depending on the subtype." (PMID 33799951, 2021). "Adding to the complexity, AR expression is prognostic of both improved and worse patient outcomes depending on protein vs. mRNA detection platforms, discrepancies in binning of expression levels, breast cancer subtype, and clinical endpoints." (PMID 34680352, 2021). "This concomitant expression of the AR in both basal and hormone-sensing cell subpopulations may explain the dichotomous role exerted by the AR in the different breast cancer settings." (PMID 35008851, 2021). "The biological mechanism of AR in breast cancer varies according to its ER status." (PMID 32290220, 2020). "Importantly, carcinomas with apocrine differentiation usually have poorer prognosis than NST invasive carcinomas, possibly because of the high expression of AR in this type of breast cancer." (PMID 32587770, 2020). "Moreover, it has been shown that the three hormone receptors (ERa, PR and AR) are able to interact with each other in the cytoplasm of different breast cancer cells to control many biological responses induced by sex steroids." (PMID 33266334, 2020). "These indicates that breast cancers patients from Ethiopia may have favorable prognosis and could also benefit from progresses in AR targeted treatments under development." (PMID 32374753, 2020).
breast carcinoma (continued). "AR exhibits different behavior depending on the breast cancer subtype." (PMID 31952272, 2020). "Biological insight into AR-positive breast cancer reveals that AR may cross-talk with several vital signaling pathways, including key molecules and receptors." (PMID 31952272, 2020). "Relatively scarce information is available about the role of androgens and the AR in breast cancer." (PMID 32218303, 2020). "Our study reveals AR is expressed in a significant number of breast cancers patients and this may indicate that breast cancers cases in Ethiopia have favorable prognosis and could benefit from progresses in AR targeted treatments." (PMID 32374753, 2020). "Although the prognostic value of AR immunoreactivity in TNBC remains controversial, preclinical and clinical data have revealed that patients with ER-negative/AR-positive breast cancer might be candidates for treatment with AR antagonist." (PMID 32697770, 2020). "Interestingly, it has been noticed that the androgen receptor (AR) is expressed in 70–90% of the BC incidents, and that it plays a crucial role in breast cancer pathology and progression." (PMID 31952272, 2020). "First, we examined AR and microRNAs' expression according to breast cancer subtype." (PMID 32373367, 2020). "Thus, to identify novel metastatic markers, we evaluated the expression levels of AR; miR-185 and miR-205, both of which have been confirmed to target AR; and miR-21, transcription of which is regulated by AR, in breast cancer samples (n = 89)." (PMID 32373367, 2020). "For example, the androgen receptor in breast cancer behaves differently than in the prostate." (PMID 33076284, 2020). "Therefore, through direct or indirect mechanisms, AR signaling likely also plays an important role in controlling cell cycle progression in breast cancer." (PMID 33062889, 2020). "AR is expressed in all stages of breast cancer (in-situ, primary and metastatic disease) and several studies show AR may play different prognostic role in ER-positive and ER-negative breast cancers." (PMID 32374753, 2020). "Recent data suggest that AR signaling may also be important in breast cancer, glioblastoma, and additional tumor types with AR expression." (PMID 33062889, 2020). "Moreover, postmenopausal women exhibit minor side effects, and the treatment is currently being investigated in a phase II clinical trial for patients with metastatic or locally-advanced ER+ and AR+ breast cancer (NCT02463032)." (PMID 31952272, 2020). "AR is frequently expressed in breast cancers and proposed to be a target in the disease." (PMID 32484822, 2020). "More recently, a role for AR in the progression of breast cancer has been described." (PMID 33062889, 2020). "AR positive expression was defined as IHC > 10% breast cancer tumor cell nuclear staining." (PMID 32587770, 2020). "There are compelling evidences that AR expression may be used to further refine breast cancer molecular subtyping with prognostic and therapeutic implications." (PMID 32374753, 2020). "Besides, AR and PPARγ are still complicated targets for breast cancer treatment because studies gave contradictory conclusions." (PMID 33246450, 2020). "Recently, the androgen receptor (AR) emerged as a possible target for breast cancer therapy." (PMID 32307594, 2020). "AR expression rate is also reported to be different across breast cancer subtypes." (PMID 32290220, 2020). "The relative roles of ER and AR in breast cancer proliferation are controversial." (PMID 32326308, 2020). "Despite having identified the presence of AR expression in breast cancer many years ago15, little is known about the role of androgen signaling in breast cancer, though its importance as a potentially effective therapeutic target is increasingly appreciated and will be discussed herein." (PMID 33062889, 2020). "This may explain why women with ER-positive, AR-positive breast cancers have shown a better prognosis compared to all other AR/ER combinations)." (PMID 32928183, 2020).
breast carcinoma (continued). "In breast cancer imaging, studies to visualize the AR expression are limited." (PMID 32218303, 2020). "Future work may assess PARPi in combination with anti-AR therapies for the treatment of AR+ breast cancers." (PMID 33062889, 2020). "Overall, the molecular characterization of CTCs from advanced TNBC patients identifies highly specific biomarkers with potential applicability as noninvasive prognostic markers and reinforced the value of TIMP1 and AR as potential therapeutic targets to tackle the most aggressive breast cancer." (PMID 32012729, 2020). "More extensive study of the heterogeneity of AR in breast cancer is necessary." (PMID 32587770, 2020). "The prognostic role of AR also varies across breast cancer subtypes." (PMID 32290220, 2020). "Ongoing and completed clinical trials continue to assess the efficacy of AR blockade as a monotherapy for patients with AR+ breast cancers (NCT01889238, NCT01842321, NCT00755885, NCT01808040, NCT01990209, NCT02580448, NCT03383679, NCT02348281, NCT02130700, NCT02067741)." (PMID 32117061, 2020). "The AR signaling pathway plays an important role in initiation and progression of many hormone-related cancers including prostate, bladder, kidney, lung, and breast cancer." (PMID 33082888, 2020). "The value of AR as a biomarker and therapeutic target in breast cancer remains elusive." (PMID 31952272, 2020). "Further studies are needed to validate the prognostic role of AR in breast cancer." (PMID 32290220, 2020). "Methodology and reagents to quantify AR expression by breast cancer cells are in development." (PMID 35582612, 2020). "Further, discerning the intricacies and crosstalk between AR and ER signaling may also provide advancements for treatment of AR+, ER+ breast cancers." (PMID 33062889, 2020). "Our study shows AR expression is significantly high among ER+ breast cancer patient." (PMID 32374753, 2020). "Moreover, androgen-receptor (AR) positivity characterizes 10–15% of TNBC, and is often associated with clinicopathological features resembling HR+/HER2- breast cancer (BC), with frequent association with older age and late relapse." (PMID 32899209, 2020). "These are features seen in basal like breast carcinoma which was also shown to be associated with an AR – negative status." (PMID 32928183, 2020). "The concordance of more than 70% of AR expression in primary and metastatic breast tumors implies that AR may be a new marker and a potential therapeutic target among AR-positive breast cancer patients." (PMID 31952272, 2020). "We investigated the prognostic influence of androgen receptor (AR) on breast cancer." (PMID 32290220, 2020). "Finally, phase I/II clinical trials continue to inform drug development and clinical practice, including trials of newer generation antiandrogen agents in women with AR+ breast cancer." (PMID 33062889, 2020). "Additionally, new compounds acting either as ERa modulators or degraders, AR modulators or antagonists, and PR modulators are under clinical trial for treatment-resistant breast cancer or to prevent progression." (PMID 33266334, 2020). "Androgen receptor (AR) expression is emerging as a prognostic biomarker in breast carcinoma (BCa)." (PMID 32928183, 2020). "Although AR was shown to play an important role in prostate and breast cancers, its differential role in men and women with PTC remains unclear." (PMID 32365531, 2020). "In women, AR(CAG)n has been associated with testosterone levels, bone mineral density and obesity as well as cancers of the breast and ovaries." (PMID 32593802, 2020). "Although it has been suggested that miR‐328‐3p can mediate androgen receptor (AR) in breast cancer cells, the interaction between hsa_circRNA_002178 and miR‐328‐3p as well as the underlying mechanism is largely unknown." (PMID 31957232, 2020).
breast carcinoma (continued). "However, the role of AR in breast cancer is emerging only recently because of the increased interest among researchers in breast cancer to understand a disease which is so heterogenous in its molecular feature and limited treatment options." (PMID 32374753, 2020). "This might explain the relatively high rate of cytoplasmatic localized AR in our study as mitotic CTCs seem to be a common event in advanced breast cancer." (PMID 31718606, 2019). "Cats tend thus to have a higher AR expression in FMCs than women with breast cancer." (PMID 31888566, 2019). "The authors highlighted the role of the AR in breast cancer bone metastasis and suggested that metastatic breast cancer patients may benefit from an AR target therapy." (PMID 31681412, 2019). "The results show a statistically significant positive correlation between USP14 expression and AR expression in breast cancer, suggesting that the increased USP14 expression might have resulted from elevated AR expression." (PMID 31126320, 2019). "In estrogen-dependent breast cancer cell proliferation, these findings reinforce the possibility that targeting AR signalling may potentiate the effectiveness of anti-estrogen adjuvant therapies." (PMID 31684907, 2019). "We provide evidence that AR mRNA predicts response to chemotherapy in breast cancer patients." (PMID 31728025, 2019). "In the present study, we sought to explore whether both inhibition of AR signal and degradation of AR protein would synergistically inhibit the growth and progression of breast cancer cells." (PMID 31126320, 2019). "Therefore, we predicted that a treatment combining enzalutamide and USP14 inhibition should be more effective than the treatment with either single agent in terms of suppressing AR signaling in AR-positive breast cancer cells." (PMID 31126320, 2019). "Therefore, this is the first study which analyzed in detail the relationships between sPSA and various biological characteristics of breast cancer and, in particular, the relation to serum androgen level and AR expression in the primary tumor tissue." (PMID 31664946, 2019). "AR dependency has also been suggested in a subset of ER-negative, AR-positive breast cancers." (PMID 31664946, 2019). "Our data suggest that sPSA may reflect tumor biological properties including AR activity in post-menopausal breast cancer." (PMID 31664946, 2019). "Androgen serum levels in women are generally much lower than in men, possibly leading to the reduced activity of the AR in breast cancer patients, which may explain the cytoplasmic localization of the receptor in some cases." (PMID 31718606, 2019). "Then, considering that data have been reported in the literature only on the role of AR/ER ratio as unfavorable prognostic marker in primary tumor of early breast cancer patients, we performed a study in a different BC population, who presented disease relapse." (PMID 31110518, 2019). "In addition to the prognostic role of AR in breast cancer patients, there is growing evidence that AR predicts response to chemotherapy treatment rather than to endocrine treatment with the worst response rates in patients with low AR expression." (PMID 31728025, 2019). "The biological significance of the AR-induced inhibition of cyclin D1 expression is highlighted by clinical studies in ERα-positive breast cancers, showing a better response to adjuvant therapy in cancer patients with cyclin D1 low/moderate expression than those with high expression of cyclin D1." (PMID 31684907, 2019). "Clinical trials testing AR-targeting therapies in breast cancer have been conducted." (PMID 31664946, 2019). "We wanted to find out whether the inhibition of the growth of ER(+)/AR(+) breast cancer cells of the other investigated sterols also results from down-regulation of cyclin D1." (PMID 31235695, 2019). "The compound significantly reduced AR levels in AR-expressing breast cancer MCF7 cells." (PMID 31192191, 2019).